TNF (tumor necrosis factor)
Diseases named in the same sentence as TNF in open-access papers (continued):
Sharing a sentence is not in itself a finding about the gene and the disease.
breast carcinoma (continued). "One of the key mechanisms of TNF-α in breast cancer involves its ability to promote tumor growth by upregulating the oncogenic protein hepatitis B X-interacting protein (HBXIP), thereby enhancing cell proliferation and survival." (PMID 40430573, 2025). "Another study reported that serum TNF-α was markedly elevated in patients with stage III breast carcinoma compared to controls (p < 0.001), and TNF-α levels correlated with tumor stage and lymph node status." (PMID 41007766, 2025). "A 2018 study found that obese postmenopausal breast cancer survivors can reduce inflammation (IL-6 and TNF-α) through a combination of resistance and aerobic exercise training." (PMID 40584290, 2025). "Human breast cancer cells stimulated with TNF-α showed accelerated IKK activation and increased expression of NF-κB target genes when Tob was deleted." (PMID 40169858, 2025). "C. aspersum extract was also found to induce necrosis of the Hs578T breast cancer cell line and significantly increase the expression of TNF-α." (PMID 41226159, 2025). "This study employed multiple modes of Atomic Force Microscopy (AFM) to investigate the impact of TNF-α on breast cancer cells." (PMID 41415204, 2025). "Mechanistically, TNF-α binds TNF receptors on breast cancer cells, triggering NF-κB and AP-1 signaling cascades that upregulate genes involved in proliferation, invasion, angiogenesis, and resistance to apoptosis." (PMID 41007766, 2025). "The anticancer mechanisms of LNE in breast cancer are primarily associated with the PI3K-Akt signaling pathway, EGFR tyrosine kinase inhibitor resistance, TNF signaling pathway, and HIF-1 signaling pathway." (PMID 40729015, 2025). "Murine mammary cancer cells were infected with SFV delivering tumour necrosis factor-α (TNFα) or interferon-γ (IFNγ) genes." (PMID 40547518, 2025). "TNF produced by cells of bone‐marrow origin was responsible for significantly delaying mammary tumor growth in a mouse model." (PMID 40977146, 2025). "miR-21 is elevated in canine mammary tumors and positively correlates with gene expression of IL-6 and TNF-α and also with the proliferation index (Ki67 index) of tumour cells." (PMID 40028181, 2025). "Proinflammatory factors, such as TNF-α, IL-1β, and IL-6, influence the development and progression of mammary tumors." (PMID 40526430, 2025). "The NOD-like receptor pathway is also an important pathway for activating the body’s immune signal, promoting the secretion of inflammatory factors such as TNF-α, and further killing breast cancer cells." (PMID 38244591, 2024). "When we exposed human macrophages to resistant breast cancer-derived EVs, we observed a pro-inflammatory profile with increased TNF-α, IL-1β, and IFN-γ expression, exhibiting anti-tumoral characteristics." (PMID 39474419, 2024). "A cohort study done in in early-stage breast cancer patients investigated the changes in cytokine (IL-1β, TNF-α and IL-4) levels before and after chemotherapy demonstrated higher IL-4 levels in patients after receiving the chemotherapy treatment." (PMID 39355088, 2024). "The pathways discussed and found to be consistently affected by the reported nutraceuticals in breast cancer-Nf-κB, TNF-α/IL-1β, PI3K/Akt, and MAPK/p38-are interconnected and offer the most relevant molecular targets for therapeutic protocols." (PMID 39728433, 2024). "Thus, while decreased KRas, beta-catenin, and TNFα signaling likely underly the attenuation of tumor growth by Hpa2-Nuc in pre-clinical models, activation of the immune system likely play a suppressive role in breast cancer patients in which nuclear localization of Hpa2 was retained." (PMID 38519456, 2024). "Polysaccharide peptide (PSP) acts by upregulating the TLR4-TIRAP/MAL-MyD88 signaling pathway in peripheral blood mononuclear cells (PBMCs) from breast cancer patients, inducing the secretion of IL-12, IL-6, and TNF-α, thus serving as an immune adjuvant." (PMID 38347830, 2024).
breast carcinoma (continued). "According to the literature, TNF-α supports the growth of the tumor, but there are also data showing that it differs between breast cancer cells." (PMID 39175950, 2024). "Loss of Mgat5 in breast cancer led to a decrease in tumor growth and an increase in the production of IFN-γ and TNF-α in splenocytes." (PMID 38912584, 2024). "We found that TGF-β/TNF-α co-stimulation resulted in hypermethylation at histone H3K36 residues in breast cancer cells, compared to cells treated with TGF-β or TNF-α alone." (PMID 39351229, 2024). "When comparing the levels of TNF-α in breast cancer patients (stage III) to those with stage I cancer and control patients (healthy), stage III levels were elevated." (PMID 38793599, 2024). "To verify the mechanism underlying the inhibitory effect of Orp breast cancer inhibition, we evaluated the expression of WNT/β-catenin signaling-related proteins in mouse breast cancer tumor tissues and TNF-α-challenged MCF-7 breast cancer cells." (PMID 38356709, 2024). "Taken together, co-expression of elevated MMP-9 with of TGF-β and TNF-α in the human breast cancer tissues is corroborated to our in vitro findings indicating the synergistic role of TGF-β and TNF-α in potentiating MMP-9 in breast cancer cells." (PMID 39351229, 2024). "These confirm the concept that M-DCsTNF target and kill breast cancer by producing TNFα when an IAP antagonist is present." (PMID 39105847, 2024). "In cultured breast cancer cells, TNF-α, via the induction of the production of MMP-2 and MMP-9 in tumor-associated macrophages (TAMs), can contribute to the invasion of neoplastic cells into surrounding tissues." (PMID 39339184, 2024). "We found that combined treatment of TGF-β/TNF-α synergistically upregulates the production of MMP-9 by the MCF-7 breast cancer cell line." (PMID 39351229, 2024). "Training programs with Taichi 120 min a week for 3 and 4 months, respectively, are reportedly to show the trend to decrease TNF-α and IL-6 in breast cancer survivors with insomnia and in older adults with insomnia." (PMID 38635535, 2024). "Taken together, PARP1 > 6, p50 > 2, and TNF-α > 4 have a certain value in predicting breast cancer metastasis, and the predictive value is better when they are combined for diagnosis (Secombine = 97.94%, Spcombine = 71.13%)." (PMID 38388665, 2024). "To validate the modulation of cell proliferation and cell cycle progression by LINC01929 through the TNF pathway, we performed LINC01929 knockdown and TNF‐α stimulation experiments in breast cancer cells." (PMID 39586790, 2024). "Our results show that inhibition of histone methylation by BIX 01294 attenuated the synergistic effect of TGF-β/TNF-α co-stimulation on MMP-9 expression in MDA-MB-231 breast cancer cells." (PMID 39351229, 2024). "M-DCsTNF can recognize breast cancer and produce TNF to induce cancer cell apoptosis rapidly when an IAP antagonist is given to degrade IAP proteins." (PMID 39105847, 2024). "Altogether, these results demonstrate that TGF-β priming amplifies the TNF-α-mediated induction of MMP-9 in breast cancer cells." (PMID 39351229, 2024). "Serum levels of TNF-α (an inflammatory agent highly expressed in breast carcinomas) increased following DMBA exposure." (PMID 38818375, 2024). "Next, we determined activation of the p38 and Smad2/3 signaling pathways in response to TGF-β/TNF-α co-stimulation in MDA-MB-231 breast cancer cells." (PMID 39351229, 2024). "One study stated that breast cancer cell-secreted TNF-alpha and TGF-beta drive the expression of MMP-9 in stromal fibroblasts." (PMID 39351229, 2024). "Tumour necrosis factor-α (TNF-α) is an important inflammatory cytokine found in the TME that is involved in all stages of breast cancer growth, affecting cell proliferation and survival, epithelial-to-mesenchymal transition (EMT), metastasis and recurrence." (PMID 38956273, 2024).
breast carcinoma (continued). "In breast cancer patients, the serum levels of TNF-α and IL-6 are significantly elevated and the hippocampal volume is reduced following chemotherapy." (PMID 38348396, 2024). "Similar results have been seen in MCF-7 breast cancer cells when treated with BIX 01294 before TGF-β/TNF-α co-stimulation." (PMID 39351229, 2024). "DTX has been reported to initially enhance the TNF-α release from breast cancer cells in a time-dependent manner but reduces the TNF-α release in a concentration dependent manner within 48h47." (PMID 39289425, 2024). "In MDA-MB231 and MDA-MB453 breast cancer cells treated with metformin, the expression of IL-12 and TNF-a cytokines was increased." (PMID 38358644, 2024). "As a proinflammatory cytokine, the aberrant expression of TNF-α was also identified in multiple malignancies including prostate, ovarian, liver, and breast cancer." (PMID 38520006, 2024). "Most of the 11 TNF signaling pathway targets we tested were targets of breast cancer doxorubicin resistance, except for CXCL1." (PMID 39000182, 2024). "When the body detects breast cancer cells, innate immune cells like lymphocytes and macrophages secrete cytokines like tumor necrosis factor (TNF), transforming growth factor (TGF), and interleukins (IL)." (PMID 38726321, 2024). "We further demonstrate that TGF-β priming and Smad2/3 signaling drive synergy with TNF-α to promote MMP-9 expression in breast cancer cells." (PMID 39351229, 2024). "For example, the activation of TNF-α upregulated ESM1 expression by the RelB subunit of NF-κB in breast cancer cells." (PMID 39309430, 2024). "Jacaranone also inhibits TNF-induced IκBα degradation in breast cancer cells (MDA-MB-231), cervical cancer cells (HeLa), and prostate cancer cells (PC3)." (PMID 39769432, 2024). "He and colleagues demonstrated that the inhibition of PI3Kγ with the natural compound baicalein potentiates the M1 macrophage polarization and inhibits tumor growth via NF-κB/TNF-α inflammatory signaling in both breast cancer and melanoma mouse." (PMID 38397187, 2024). "TNFα has been confirmed to promote the growth, migration, and invasion of various tumors, such as breast cancer, colorectal cancer, and gastric cancer." (PMID 38739004, 2024). "A study that examined 93 breast cancer specimens revealed a positive correlation between TNF‐α expression on tumour cell surfaces and lymph node metastasis." (PMID 39586790, 2024). "Previous studies have also demonstrated that the TNF pathway can improve chemoresistance in bladder and breast cancers by inducing cell differentiation." (PMID 39473903, 2024). "The breast cancer cells showed mesenchymal phenotypes and the downregulation of K18 under TNF-α alone or TGF-β1/TNF-α costimulation, and, interestingly, under TGF-β1 stimulation alone there was only K18 downregulation without any changes in EMT markers." (PMID 39502314, 2024). "One of the cytokines, tumor necrosis factor-alpha (TNF-α), is involved in brain metastasis of primary breast cancer." (PMID 38726321, 2024). "All isolated compounds exhibited notable cytotoxicity against breast cancer cells and had potent inhibitory effects on the production and release of nitric oxide (NO) and tumor necrosis factor-α (TNF-α) in macrophage cells induced by LPS." (PMID 38563878, 2024). "In cultured cells derived from mammalian breast cancer, TNF-α is a potent activator of immune cells via the induction of inflammatory cytokines such as IP-10." (PMID 39684820, 2024). "Inmacrophages, endothelial cells, hepatocytes, and tumor cell lines, such as theMCF7 breast cancer cell line, ceramides have been shown to mediate the cellulareffects of the tumor necrosis factor-α (TNF-α) receptor." (PMID 39188263, 2024). "Inflammation can severely damage breast tissue and facilitate breast cancer development by increasing proinflammatory cytokines like TNF-α and interleukins Tumor cells have shown resilience against chemotherapy through various mechanisms." (PMID 38726321, 2024).
breast carcinoma (continued). "The TNF-α nanobody inhibited breast cancer cell proliferation induced by human TNF-α in a dose-dependent manner." (PMID 38341580, 2024). "PARP1 > 6, p50 > 2, and TNF-α > 4 have a certain predictive effect on breast cancer metastasis, and the predictive effect is better when they are combined in diagnosis." (PMID 38388665, 2024). "A similar study in breast cancer showed that PBMC-derived macrophages treated with cancer cell conditioned media and cisplatin had increased IFNγ, IL6, and TNFα signaling, pathways typically associated with M1-like phenotypes." (PMID 39287565, 2024). "It was demonstrated that women with advanced breast cancer frequently experience pain and have high systemic levels of TNF-α and IL-1β." (PMID 38940936, 2024). "In line with this, melanoma also exhibited the largest concentration of IL-1β, TNFα, and Sirtuin-1, which was followed by the concentration determined in mammary carcinoma homogenates." (PMID 38698774, 2024). "The heatmap of the Pearson correlation returned by TIMER.2 shows significant positive correlations with TNF in colon, rectal and breast cancer and glioblastoma, which implies a high stimulation of TRPA1 in inflammatory conditions." (PMID 39770499, 2024). "Our in vitro findings are corroborated by co-expression of elevated MMP-9 with TGF-β and TNF-α in human breast cancer tissues." (PMID 39351229, 2024). "The western blot analysis confirmed the anticipated time- and dose-dependent inhibitory effects of jacaranone on TNFα-induced IκBα degradation in breast cancer cell MCF7 cell." (PMID 39769432, 2024). "For instance, the mRNA and protein levels of TNF-α were both upregulated in tumor and stromal cells of breast cancers with worse prognosis." (PMID 38520006, 2024). "Another study describes that enhancement of TAK1 activation by TGF-β1 and TNF-α synergistically induces epithelial to mesenchymal transition in breast cancer cells." (PMID 39351229, 2024). "Breast cancer cells that reside in the bone ECM induce osteoclast formation by releasing tumor necrosis factor-α (TNF-α), parathyroid hormone-related peptide (PTH-rP), prostaglandin E2 (PGE2), interleukins, and leukemia inhibitory factor (LIF)." (PMID 38317174, 2024). "Breast cancer tissue samples that stained intensely for TNF-α and TGF-β expression revealed markedly increased MMP-9 expression." (PMID 39351229, 2024). "After the activation of PI3K/AKT in the breast cancer cells, the expression of IL-6, IL-1β, and tumor necrosis factor-α (TNF-α) in breast cancer cells is increased." (PMID 36624542, 2023). "Collado-Hidalgo’s team conducted research on the dependence between markers of fatigue and inflammation, and their results showed increased production of interleukin IL-6 and TNF-α in breast cancer survivors with symptoms of fatigue." (PMID 36834426, 2023). "In a mouse xenograft model of human breast cancer, TNFα enhanced the cytotoxicity exerted by combined chemotherapy with docetaxel, 5-fluorouracil, and cisplatin." (PMID 37455828, 2023). "Together, these data suggest that EPS activates an inflammatory response in sensitive breast cancer cells, possibly through activation of TNF, interferon/JAK-STAT, and/or NF-κB signaling." (PMID 38074643, 2023). "Exosomal miR‐183 derived from breast cancer cells elevates the levels of TNF‐α, IL‐6, and IL‐1β in macrophages." (PMID 36705422, 2023). "TNF‐α in breast cancer stem cells induces vascular cell adhesion molecule 1 (VCAM‐1) to promote angiogenesis, and the formation of PMN which is induced by breast‐liver organ crosstalk." (PMID 37902101, 2023). "It was studied in an orthotopic syngeneic model of breast cancer in which inflammation was decreased by blocking the actions of TNFα with Infliximab." (PMID 38201482, 2023).
breast carcinoma (continued). "Among the fifteen best-ranked ferroptosis genes in breast cancer, eleven harbored some association with “extracellular matrix remodeling” literature in the PUBMED database, especially TNF, SET, and IL6, found to be highly cited in this specific literature." (PMID 37681908, 2023). "Significantly reduces the IL-6, IL-1, TNF- levels, protein, and nucleic acid content of breast cancer cells MCF-7." (PMID 36742434, 2023). "In breast cancer cells, TNFα increases the glycolysis, lactate export, and expression of the glucose transporter 1 (GLUT1) and reduces the mitochondrial mass, offering an advantage adaptive to nutrient deprivation." (PMID 37107188, 2023). "The major component of Rhizoma Coptidis is berberine; it can induce human breast cancer cell apoptosis by upregulating TNF-α and interferon-β in a time- or dose-dependent manner." (PMID 36831555, 2023). "We also found that common cancer-related adverse reactions of five TNFα inhibitors include skin cancer, breast cancer, and basal cell carcinoma." (PMID 37554981, 2023). "In terms of fibronectin production, the breast cancer cells used in our study were more responsive to IL-1β than to TNF-α or IL-6." (PMID 36922898, 2023). "The inducible isoform COX-2 responds to TNF and p38/NF-κB activation and has been found to be protective against breast cancer." (PMID 37834179, 2023). "Women with breast cancer improved stimulated TNFα and IFNγ following a 16 week exercise intervention, which suggests that training status influences this response." (PMID 37325799, 2023). "Studies in breast cancer indicated that TNF-α was detected at a higher level in invasive cancer than in benign tissue, while malignant breast cancer tissue had higher TNF-α levels." (PMID 37212877, 2023). "For example, breast cancer cells secrete pro-inflammatory cytokines such as IL-6 and tumor necrosis factor (TNF-α) that can promote adipose tissue inflammation and disrupt normal adipose tissue function." (PMID 37174117, 2023). "This is significant because TNFα is linked to MCF-7 cancer cell lines, and it enhances luminal breast cancer cell proliferation by upregulating aromatase." (PMID 37745072, 2023). "Recent evidence from a breast cancer cell line and a human melanoma cell line suggests that Snap29 plays a role in the TNFα-NF-κB-FOXP3 signaling axis, and silencing Snap29 promotes tumor cell migration." (PMID 36614195, 2023). "In summary, we have developed a nomogram based on two cytokines including IL-4 and TNF-α to predict OS of breast cancer and investigated their correlation with blood test indicators." (PMID 37007080, 2023). "designed a 3D in vitro model composed of breast cancer cells, human MSCs and fetal osteoblasts, and demonstrated that cytokines secreted by osteoblasts (e.g. TNFα, MCP1) were able to induce dormancy in the cancer cells." (PMID 37182144, 2023). "We also established that TNF-α increases ATX expression in the 4T1 breast cancer cell line and increases the clone-forming ability, which depends on the activation of NF-κB." (PMID 38201482, 2023). "Regular exercise in breast cancer survivors after primary treatment has consistently shown to decrease pro-inflammatory cytokines (IL-2, IL-6, IL-8, TNF-α) and increase anti-inflammatory cytokines (IL-10)." (PMID 37507961, 2023). "For instance, several studies have demonstrated a noteworthy elevation in the concentrations of IL-5, IL-6, IL-7, and TNF-α in both the pathological tissue and systemic circulation of breast cancer patients, as compared to healthy individuals." (PMID 37910571, 2023). "There is evidence that TNF-α can be detected in biopsies from human cancers, such as breast cancer and ovarian and renal cancer." (PMID 37895145, 2023). "In breast cancers, the expression of TNFα correlates with higher tumor cell proliferation, higher grade of malignancy, increased tendency to metastasis and a general poor prognosis." (PMID 36941680, 2023).